C3 (complement C3)
Diseases named in the same sentence as C3 in open-access papers (continued):
Sharing a sentence is not in itself a finding about the gene and the disease.
Cachexia (3 papers, 2020 to 2025). Severe weight loss, wasting of muscle, loss of appetite, and general debility related to a chronic disease. "Our results revealed a marked increased muscular production of several acute phase reactants (APR: Haptoglobin, Serine protease inhibitor A3N, Complement C3, Serum amyloid A-1 protein) which are released in the circulation during C26 cancer cachexia." (PMID 33142864, 2020). "Since muscles of cancer-free C3–/– mice were significantly smaller than those of cancer-free WT mice, we cannot rule out that lower starting muscle mass leads to a differential response to cachexia." (PMID 40198138, 2025).
cholangiocarcinoma (3 papers, 2015 to 2020). A carcinoma that arises from the intrahepatic biliary tree (intrahepatic cholangiocarcinoma) or from the junction, or adjacent to the junction, of the right and left hepatic ducts (hilar cholangiocarcinoma). "Fourteen proteins (6%) were identified as more abundant in cholangiocarcinoma, including such proteins as intercellular adhesion molecule 1, ceruloplasmin, haptoglobulin, complement c3, and -c4b." (PMID 25304323, 2015).
chronic heart failure (3 papers, 2013 to 2025). "Proteomics of plasma have shown that decreased C3 levels are associated with poorer survival in congestive heart failure." (PMID 38527066, 2024).
chronic hepatitis B (3 papers, 2022 to 2024). "Serological tests as per the guidance of the US National Institute for Diabetes, Digestive and Kidney Diseases include tests for chronic hepatitis B and C, antinuclear antibodies, rheumatoid factor, complement levels (C3/C4), serum and urine protein electrophoresis, and a free light chain assay." (PMID 38256482, 2024).
co-infection (3 papers, 2021 to 2025). "The upregulation of C3 reflects a localized immune defense specifically tailored to the gills, which serve as a primary barrier tissue after subsequent co-infection with M. cerebralis." (PMID 40943072, 2025). "In the present study, significant upregulation of IL-1β, transferrin, and C3 gene expression was observed post-turmeric oil treatment in P. hypophthalmus with co-infection conditions." (PMID 36119096, 2022). "In gills, Mc+ fish showed moderate cytokine-related gene upregulation, while Tb+ (1 day after co-infection with M. cerebralis) fish displayed increased expression of humoral response genes (C3, immunoglobulin pathways) but suppression of genes involved in B cell development." (PMID 40943072, 2025). "In contrast, Tb+ fish (subsequent co-infection with M. cerebralis) exhibited a highly potent innate immune response, including substantial upregulation of CRP and C3, activation of IL-1 signaling, and enhanced humoral immunity." (PMID 40943072, 2025).
cold agglutinin disease (3 papers, 2022 to 2025). Cold agglutinin disease is a type of autoimmune hemolytic anemia defined by the presence of cold autoantibodies (autoantibodies which are active at temperatures below 30B0C). "Patients with cold agglutinin disease have a steady state of depleted C3 and C4, and infusion of plasma could worsen haemolysis." (PMID 36102159, 2022).
deficiency (3 papers, 2014 to 2022). "For reducing complement activation due to FH deficiency, drug compounds targeting C3, FB, C5, FP, C3b, C3bB, and C3 convertase are predicted to be efficacious in reducing disease severity." (PMID 35517827, 2022). "For inhibiting complement activation due to FH deficiency, drug compounds targeting C3, FB, C5, FP, C3b, C3bB, and C3-convertase at 90% inhibition are predicted to be efficacious in reducing disease severity." (PMID 35517827, 2022). "C3 deficiencies are extremely infrequent, but patients usually suffer from repeated infections, and in some cases, immune complexes-related disorders are reported." (PMID 25886501, 2015).
dermatitis (3 papers, 2013 to 2022). An inflammatory process affecting the skin. "Detection of immunoreactants including IgG, IgM, IgA, and C3 by direct immunofluorescence (DIF) from skin is useful for distinguishing lupus lesions from other skin disorders." (PMID 23940681, 2013).
dysferlinopathy (3 papers, 2022 to 2024). "Since complement pathways contribute to disease progression in dysferlinopathy, C3 and C5 serum levels were evaluated in BlAJ at 6 and 12 months vs 12 m BlAJ+ONX." (PMID 36402750, 2022). "Furthermore, genetic ablation of C3 in dysferlin-deficient mice reduced disease severity, indicating that activation of C3 accelerates muscle damage in dysferlin-null mice and that complement-mediated injury is central to the pathogenesis of dysferlinopathy." (PMID 39123261, 2024). "Complement C3 plays a central role in the activation of the complement system, and complement‐mediated muscle damage is at the heart of dysferlinopathy pathogenesis, suggesting that targeting the complement system may be a treatment for the disease." (PMID 36325691, 2022).
endometritis (3 papers, 2023 to 2025). An acute or chronic, usually bacterial infectious process affecting the endometrium. "Additionally, in contrast to cows with sub-clinical endometritis, the gene expression profiles of C3, CXCL8, LTF, TLR2, and TRAPPC13 were temporally changed in healthy cows’ circulating WBC during the postpartum period." (PMID 37756095, 2023). "Specific mRNA expression patterns of C3, C2, LTF, PF4, and TRAPPC13 are present in the blood and endometrium of dairy calves with subclinical endometritis." (PMID 37756095, 2023). "Additionally, C3, C2, LTF, PF4, and TRAPPC13 had unique mRNA expression patterns in the blood and endometrial tissue of dairy cows with subclinical endometritis." (PMID 37368756, 2023).
Fabry disease (3 papers, 2023 to 2024). Fabry disease (FD) is a progressive, inherited, multisystemic lysosomal storage disease characterized by specific neurological, cutaneous, renal, cardiovascular, cochleo-vestibular and cerebrovascular manifestations. "The interaction of C3 convertase with C3b subsequently leads to the formation of C5 convertase, which cleaves C5 into C5a in the context of Fabry disease." (PMID 39596318, 2024). "Elevated levels of complement 3a (C3a), C5a, and their precursor C3 are observed in the plasma, serum, and tissues of patients with Fabry disease, correlating with significant endothelial cell abnormalities and vascular dysfunction." (PMID 39596318, 2024). "Both the mouse model of Fabry disease and a small subset of Fabry patients with glomerulopathy exhibit renal tissue deposition of C3, predominantly in the mesangial area." (PMID 39596318, 2024). "Elevated levels of several components of the complement system, i.e., C1qc, C3, iC3b, C4, and C4b, complement factor B precursors (C3/C5 convertase) have been observed in the serum, plasma, and brain of patients with Fabry disease." (PMID 37189685, 2023).
Fever (3 papers, 2020 to 2024). Body temperature elevated above the normal range. "Fever duration > 12 d, IL-8 > 2,721.33 pg/ml, LDH > 482 U/L and C3 < 1.02 g/L were independent risk factors for PB in children with MPP." (PMID 34733807, 2021).
gingivitis (3 papers, 2016 to 2022). A disorder involving inflammation of the gums; may affect surrounding and supporting structures of the teeth. "Induction of experimental gingivitis in human volunteers causes progressive complement activation (as determined by C3 conversion in gingival crevicular fluid) that is correlated with increased clinical inflammation." (PMID 27745832, 2016). "We found that MCs, C3-positive cells and C5a-positive cells were increased in TR compared to control cats and cats suffering from gingivitis, indicating that all these are involved in the destruction of the dental mineralized matrix." (PMID 33803323, 2021).
gout (3 papers, 2017 to 2023). A condition characterized by painful swelling of the joints, which is caused by deposition of urate crystals. "Moreover, increased levels of C4 can contribute to increased C4/C3 ratio in patients with gout compared with patients with AHU." (PMID 37821971, 2023).
hypertrophic cardiomyopathy (3 papers, 2021 to 2025). A condition in which the myocardium is hypertrophied without an obvious cause. "C3 level has been shown to be elevated in serum of patients with left ventricular hypertrophy, in hypertensive patients and more recently was recognized as a marker of hypertrophic cardiomyopathy." (PMID 33716957, 2021). "Proteomic profiling identified a set of six proteins with predictive value for SCD in patients with hypertrophic cardiomyopathy (HCM): thrombospondin-1 (THBS1), complement C3 (C3), aldolase A (ALDOA), Ras suppressor protein 1 (RSU1), glutathione S-transferase omega 1 (GSTO1), and talin-1 (TLN1)." (PMID 40725061, 2025). "Similarly, C3 was mainly involved in ECM receptor interaction, Calcium signalling pathway, Dilated cardiomyopathy, Hypertrophic cardiomyopathy HCM and multiple metabolism-related pathways." (PMID 36474294, 2022).
Hyponatremia (3 papers, 2016 to 2021). An abnormally decreased sodium concentration in the blood. "However, serum C3 levels which reflect the disease activity were significantly lower in SLE patients with hyponatremia than those without (p = 0.004)." (PMID 27193532, 2016).
idiopathic membranous nephropathy (3 papers, 2012 to 2020). "Pathologic diagnosis of stage I idiopathic membranous nephropathy (MN-I) requires electron microscopy or immunohistochemistry that shows a glomerular capillary staining pattern of IgG and C3." (PMID 22909298, 2012). "And C3, HLA.DQA1 has been reported in many reports with glomerular nephropathy, idiopathic membranous nephropathy, steroid-sensitive nephrotic syndrome in children, and other immune system diseases." (PMID 33215029, 2020).
immunotoxicity (3 papers, 2023 to 2024). "On the one hand, we found no significant changes in indicators of immunotoxicity, including IgG, IgM, complement C3, C4, CD4+, and CD8+ T-cell subsets, in the present study." (PMID 38020919, 2023).
intrauterine growth restriction (3 papers, 2019 to 2024). "It affects women in early pregnancy stages and is associated with fetal adverse effects: intrauterine growth restriction, premature birth, and placental insufficiency through IgG and C3 deposition in the amniotic membrane." (PMID 35888566, 2022).
ischemia reperfusion injury (3 papers, 2009 to 2023). Adverse functional, metabolic, or structural changes in ischemic tissues resulting from the restoration of blood flow to the tissue (reperfusion), including swelling; hemorrhage; necrosis; and damage from free radicals. "While there exists little data concerning the activation of complement in humans following OHCA, the importance of complement activation, and in particular C3, has been demonstrated repeatedly in the pathogenesis of ischemia-reperfusion injury in both humans and various animal models." (PMID 20150958, 2009). "In murine models of ischemia-reperfusion injury both endogenous and exogenous PTX3 were described to alleviate leukocyte recruitment following renal ischemia, while the lack of PTX3 was associated with a higher degree of apoptosis and C3 deposition in damaged cardiac tissue." (PMID 30858847, 2019). "To study the role of the C3 in the development of renal in AKI, we detected the level of C3, urinary protein excretion (UPE), BUN, and Scr in ischemia–reperfusion injury (IRI) mice." (PMID 36973754, 2023).
keratitis (3 papers, 2019 to 2025). A corneal disease that is characterized by inflammation of the cornea. "keratitis patients exhibited slightly higher levels of C3 and its cleaved products." (PMID 40521031, 2025).
lipodystrophy (3 papers, 2016 to 2025). A congenital or acquired disorder characterized by abnormal loss or redistribution of the adipose tissue in the body. "Lipodystrophy has been associated with the presence of IgG antibody C3 nephritic factor which utilizes the capacity of the adipocytes to form C3 convertase in its surroundings and induces complement-mediated lysis of adipocytes." (PMID 40554351, 2025). "Some supportive criteria were also met, namely: onset during adolescence, the absence of a family history of lipodystrophy, and low serum levels of C3." (PMID 26987365, 2016).
liver cancer (3 papers, 2024 to 2025). An epithelial or non-epithelial malignant neoplasm that arises from the liver. "Protein‐level analyses identified four trogocytosis‐ and efferocytosis‐related proteins, TGFB3, EPOR, ELANE, and C3, that may mediate these dietary effects on liver cancer susceptibility." (PMID 40895144, 2025). "This study uncovers a potential molecular mechanism by which FODMAP‐related dietary patterns may modulate liver cancer risk through the TGFB3/EPOR/ELANE/C3 signaling axis." (PMID 40895144, 2025). "MR findings suggest that higher cheese intake is associated with reduced liver cancer risk, with partial mediation through modulation of TGFB3, EPOR, ELANE, and C3 expression." (PMID 40895144, 2025). "Analysis of 21 trogocytosis‐related proteins identified three with causal associations to liver cancer: HAVCR2, CD274, and C3." (PMID 40895144, 2025). "In liver cancer, accumulating evidence suggests that C3 influences disease development by modulating the tumor microenvironment and shaping immune cell infiltration." (PMID 40895144, 2025). "Mediation MR indicated that cheese intake influenced liver cancer risk indirectly by modulating TGFB3, EPOR, ELANE, and C3 expression, accounting for 8.8%, 25%, 1.8%, and 12.7% of the total effect, respectively." (PMID 40895144, 2025). "The MR results revealed significant associations between three FODMAP dietary components, cheese, cereal, and dried fruit intake, and six liver cancer‐related proteins (ANXA2, SFTPD, TGFB3, EPOR, ELANE, and C3)." (PMID 40895144, 2025). "Among the six hub genes, C3 and DNASE1L3 are relatively low expressed in HCCLM3 and 97H liver cancer cell lines, while CTNNB1, CYBC1, IRAK1, and SERPINE1 are relatively overexpressed in liver cancer cell lines." (PMID 39055701, 2024).
liver dysfunction (3 papers, 2012 to 2025). "Clinical data analysis showed liver dysfunction (decreased albumin), immune system activation (increased globulin), and complement system activation (increased C4, C3) in PTB patients." (PMID 24484408, 2014). "For example, activated C3 drives inflammation, high TP levels indicate hemoconcentration from decreased serum water content (e.g., severe dehydration from diarrhea), low ALB and high bile acids suggest liver dysfunction." (PMID 40545549, 2025).
lymph node metastasis (3 papers, 2013 to 2021). "Importantly, we also demonstrate that protein expression of complement C3 in cancer cells decreases in the course of metastatic spread and its further decrease in lymph node metastases is linked with patients poor prognosis." (PMID 33658651, 2021).
meningioma (3 papers, 2021 to 2023). A generally slow growing tumor attached to the dura mater. "Another protein, Complement C3 (C3) has been reported to be key protein in tumorigenesis of Meningiomas." (PMID 34055594, 2021).
mucous membrane pemphigoid (3 papers, 2012 to 2024). Mucous membrane pemphigoid is a bullous dermatosis characterized clinically by blistering of the mucous membranes followed by scarring, and immunologically by IgG, IgA and/or C3 deposits on the epidermal basement membrane. "Another valuable DIF result in our study is the early identification of a few patients with exclusive oral lesions as mucous membrane pemphigoid (MMP) based on a positive reaction with IgG, IgA, and C3 immunoglobulins." (PMID 39727453, 2024).
nonalcoholic fatty liver disease (3 papers, 2016 to 2021). "This study aimed to investigate the association between serum complement C3 levels with non-alcoholic fatty liver disease (NAFLD)." (PMID 27029598, 2016).
osteosarcoma (3 papers, 2018 to 2024). A usually aggressive malignant bone-forming mesenchymal neoplasm, predominantly affecting adolescents and young adults. "Six of these genes are increased (MYOM2, VEGFA, MUC1, IHH, GLI1 and GRIA1) and seven are decreased (VCAM1, EGFR, GPC3, IGF2, GNG12, GNGT1 and C3) in localized patients with poor prognosis that either relapse or die due to osteosarcoma." (PMID 38538763, 2024). "TLR4 was pivotal promoter of inflammation which related NF‐kB and C3 signaling, and then released TNF‐α and ILs, which can induce apoptosis of osteosarcoma cells." (PMID 32822099, 2020). "Furthermore, COLEC12 knockdown could increase inflammation of osteosarcoma, in vivo and in vitro, through inducing myeloperoxidase (MPO), TLR4, NF‐κB, and C3, and expression of related inflammatory factors." (PMID 32822099, 2020).
pancreatic ductal adenocarcinoma (3 papers, 2023 to 2024). An infiltrating adenocarcinoma that arises from the epithelial cells of the pancreas. "The fungal genus Malassezia caused pancreatic ductal adenocarcinoma growth through activation of the C3 complement pathway." (PMID 37292921, 2023).
pancreatitis (3 papers, 2021 to 2026). Inflammation of the pancreas. "Crucially, both models simultaneously exposed C3‐driven complement hyperactivation, uncovering the pivotal role of the complement‐mediated inflammatory axis in pancreatitis pathology." (PMID 41090515, 2026). "Comparative studies with caerulein‐induced pancreatitis models identified C3‐mediated complement hyperactivation as a key pathological driver." (PMID 41090515, 2026).
paraneoplastic pemphigus (3 papers, 2012 to 2020). Pemphigus is a group of chronic autoimmune skin diseases characterized by blisters formation on the outer layer of the skin and the mucous membranes. "A diagnosis of paraneoplastic pemphigus (PNP) was made based on the presence of a suprabasal acantholysis associated with intercellular deposits of immunoglobulin G and C3 on basement membrane zone." (PMID 31750309, 2019). "Immunological examination of these cases revealed that in most cases only linear C3 deposits were visible on DIF, with a “ladder-like” configuration on western blotting in some cases similarly as in paraneoplastic pemphigus." (PMID 23320017, 2012).
pericarditis (3 papers, 2017 to 2024). An inflammatory process affecting the pericardium. "Low complement (C3 and C4) was associated with both pericarditis and pleurisy in our univariate cross-sectional and prospective analyses." (PMID 29118999, 2017). "Serologic tests significantly associated with both pericarditis and pleurisy were high ESR, anti-DNA, low C3 and low C4." (PMID 29118999, 2017).
pneumococcal meningitis (3 papers, 2017 to 2019). An acute purulent infection of the meninges and subarachnoid space caused by Streptococcus pneumoniae, most prevalent in children and adults over the age of 60. "Reduction of complement activation in C3-deficient mice resulted in less intracranial complications in pneumococcal meningitis, but the lack of C3-mediated opsonophagocytosis led to decreased bacterial clearance and worsened outcome." (PMID 28086930, 2017).
Poststreptococcal glomerulonephritis (3 papers, 2016 to 2024). "Given the history of recent streptococcal pharyngitis, elevated ASO and streptozyme levels, microscopic hematuria, and low C3, he was presumed to have poststreptococcal glomerulonephritis and was followed up conservatively." (PMID 27867675, 2016). "Repeat labs performed 8 weeks after hospitalization showed normal electrolytes and C3 levels, confirming the diagnosis of poststreptococcal glomerulonephritis." (PMID 27867675, 2016). "Poststreptococcal glomerulonephritis (PSGN), induced by “nephritogenic” group A streptococcal pharyngitis or skin infections, is a classic example of PIGN with diffuse proliferative and exudative glomerular histology, dominant C3 staining, some IgG deposition, and subepithelial hump-like deposits." (PMID 28280937, 2018).
Proteinuria (3 papers, 2023 to 2025). Increased levels of protein in the urine. "Proteinuria was also higher in Group 1, with patients having isolated C3 deposition and IgM and C3 co-deposition having the highest levels of proteinuria, however, this finding was not statistically significant." (PMID 37182061, 2023).